SAA1 (serum amyloid A1)
Diseases named in the same sentence as SAA1 in open-access papers (continued):
Sharing a sentence is not in itself a finding about the gene and the disease.
AA amyloidosis (continued). "AA amyloidosis is the result of overproduction and aberrant processing of acute-phase serum amyloid A1 (SAA1) by hepatocytes." (PMID 35664543, 2022). "In Caucasians, polymorphisms in the SAA1 and SAA2 (serum amyloid A1 and A2) genes have been implicated in the pathogenesis of AA amyloidosis in individuals with FFM." (PMID 36197414, 2022). "Human SAA1 amino acid sequence was selected as a positive control for all in silico analyses due to substantial reporting of AA amyloidosis in human clinical reports." (PMID 35664543, 2022). "Such elevated SAA1 plasma concentrations set the stage for the development of AA amyloidosis, especially if they remain sustained over a prolonged period of time." (PMID 34276683, 2021). "Serum amyloid A1 (SAA1) is a protein-coding gene, and the diseases most closely associated with this gene are amyloidosis Aa." (PMID 35126370, 2021). "Moreover, another SNP in the SAA1 gene at position -13 in the 5’ regulatory region (promoter region), is associated with the AA amyloidosis occurrence in both Japanese and Caucasian rheumatoid arthritisnbsp;patients, which might explain the discrepancy between previous reports." (PMID 33679725, 2020). "Systemic AA amyloidosis arises from the misfolding of serum amyloid A1 (SAA1) protein and the deposition of AA amyloid fibrils at multiple sites within the body." (PMID 28361953, 2017). "Characterization of amyloid A (AA) protein in tissues of patients suffering from reactive amyloidosis has revealed the predominant deposition of SAA1 and its proteolytic fragments as amyloid deposits." (PMID 23750222, 2013). "SAA1 is the main precursor of amyloid A, the deposition of which leads to inflammatory amyloidosis." (PMID 39001884, 2024). "SAA1 and SAA2 are both acute-phase proteins and associated with AA amyloidosis." (PMID 38568326, 2024). "AA amyloidosis is the result of the overproduction and aberrant processing of acute-phase SAA1." (PMID 35664543, 2022). "In conclusion, the polarizing effect of SAA1 towards a M1-like macrophage subset and the promotion of SAA1 fibril formation by M1 macrophages suggest revision of commonly used cell culture models for AA amyloidosis." (PMID 34276683, 2021). "Hence, in AA amyloidosis, macrophages might already be primed towards the classically activated subset and, as we have shown here, elevated levels of SAA1 could further promote macrophage M1-like polarization." (PMID 34276683, 2021). "Thus, mouse SAA1 is highly amylogenic and is often used to study AA amyloidosis in vivo." (PMID 34276683, 2021). "The known MEFV independent genetic modifiers are polymorphisms of IL-1β which is associated with disease severity and harboring alpha/alpha genotype for serum amyloid A protein 1 (SAA1) gene which increases the risk of developing AA amyloidosis without affecting FMF disease characteristics." (PMID 32806879, 2020). "SAA1 and SAA2 are acute-phase proteins that increase during inflammation (i.e., acute-phase SAA) and contribute to AA amyloidosis." (PMID 40003925, 2025). "Nevertheless, a potential involvement of SAA1 in hereditary AA-amyloidosis in cats has not been reported yet." (PMID 38136948, 2023). "AA amyloidosis was histologically confirmed in 4 patients with FMF, whose genotypes were M694I/M694I SAA1.5/15, M694I/E148Q/L110P SAA1.1/1.1, M694I/E148Q/L110P SAA1.3/1.5 and E148Q/R202Q/P369S/R408Q SAA1.3/1.5." (PMID 23437051, 2013).
lung carcinoma (21 papers, 2011 to 2025). "High levels of SAA1 expression have been reported in various cancers, including lung cancer, where its overexpression was linked to tumor development." (PMID 40565234, 2025). "We supplemented our findings with a statistical analysis of the diagnostic value of hepcidin, IL-6, TNF-a, CRP, and SAA1 in the examination and differentiation of anaemia in lung cancer patients." (PMID 36612220, 2022). "High levels of SAA1 in the blood or tumor tissue have been associated with poor prognosis in patients with lung cancer, gastric cancer, endometrial cancer, prostate cancer, melanoma and esophageal cancer and have been suggested as potential biomarkers for several types of cancer." (PMID 40299483, 2025). "Studies have found increased levels of SAA1 in cancers such as lung cancer, ovarian cancer, and breast cancer." (PMID 38951896, 2024). "SAA1 is highly expressed in lung cancer, gastric cancer, endometrial cancer, prostate cancer, melanoma, and esophagus cancer, which presented poor prognosis in patients." (PMID 37081987, 2023). "The accuracy on the Lambrechts lung cancer dataset was, however, particularly sensitive to the omittance of two genes: serum amyloid A (SAA1) and fibrinogen beta chain (FGB)." (PMID 35637521, 2022). "Elevated levels of SAA1 in the serum of cancer patients directly correlate with poor prognosis and tumor aggressiveness in various types of cancer, including lung cancer, cell renal carcinoma, melanomas and so on." (PMID 30867991, 2019). "SAA1 has also been proposed as a lung cancer biomarker, and patients with lung cancer who have higher levels of plasma SAA1 have less favorable outcomes." (PMID 29603594, 2018). "For instance, the SAA1 lung cancer biomarker, neuro-inflammation factor MMP1, the chemokine ligands (C-C motifs) CCL2, CCL5, and CCL20, and cytokines such as IL6, IL8, IL16, were all significantly modulated." (PMID 26950733, 2016). "In conclusion, a lung cancer cell itself expresses and secretes SAA1/2 upon interaction with and stimulation by immune cells residing in the tumor microenvironment." (PMID 28250368, 2014). "The expression of SAA1/2 was also greater in lung cancer cells than in normal lung cells." (PMID 37444523, 2023). "Additionally, incubating lung cancer cells with macrophages boosted the production of IL-1b and IL-6, which further encouraged the lung cancer cells to produce SAA1/2." (PMID 37444523, 2023). "However, the elevation of SAA1 in serum can be directly correlated with the unfavorable outcomes for many types of cancer such as lung cancer and cervical cancer." (PMID 29603594, 2018). "Given its route of transmission and tropism for alveolar macrophages, factors that have not been previously reported appear to be relevant to OPPV disease, such as lung cancer biomarker (SAA1), asthma biomarker (CHI3L1), and neuro-inflammation complement factor (CFB)." (PMID 26950733, 2016). "Interestingly, co-culturing lung cancer cells with macrophages resulted in increases of IL-1β and IL-6, which, in turn, stimulate lung cancer cells to induce SAA1/2 production." (PMID 28250368, 2014). "For lung cancer patients undergoing EGF receptor tyrosine-kinase inhibitor therapy, increased plasma SAA1 expression is regarded as a biomarker of poor prognosis." (PMID 35936690, 2022). "Consistent with the upregulation of SAA1 and SAA2 in lung cancer, a decreased level of Apo A-1, an APRP responsible for endogenous cholesterol removal from tissues, was observed in sera of adenocarcinoma patients with respect to healthy donors." (PMID 22229091, 2011). "Among which, SAA1, SAA2, HP, NAMPT, CHI3L1 and CHI3L2 have been reported to act as tumor promoters in multiple cancers including lung cancer, breast cancer and ovarian cancer." (PMID 38763993, 2024). "Moreover, SAA1 and SAA2 seem to be also involved in lung cancer metastasis, by inducing the expression of matrix metallopeptidase-9 (MMP-9) by macrophages." (PMID 22229091, 2011).
lung carcinoma (continued). "Thus, SAA1, SAA2, and Apo A-1 could also be considered potential biomarkers for the early detection of lung cancer." (PMID 36768828, 2023). "We found two combinations that can distinguish lung cancer patients with stage IIB from those with IIA with 100% sensitivity and 100% specificity, wherein IL-6, glucose, and LDH has an AUC = 0.8333 and the combination of CEA, IL-6, SAA1, MMP-9, and lactate an AUC = 1.0000." (PMID 34439874, 2021). "Therefore, SAA1 and SAA2 could also represent new potential therapeutic targets for the inhibition of lung cancer metastasis." (PMID 22229091, 2011). "Therefore, together with the increase in SAA1 and SAA2, the decrease in Apo A-1 could also be considered a potential lung cancer marker." (PMID 22229091, 2011). "SAA1, which was one of the significantly regulated proteins overlapping between both comparisons of AC with and without COPD vs. COPD, was reported as a biomarker for lung cancer before." (PMID 36232544, 2022).
Obesity (21 papers, 2009 to 2026). Accumulation of substantial excess body fat. "SAA1 expression is increased in high-fat diet-induced obesity and T2D and is closely associated with obesity-induced metabolic syndrome-related complications." (PMID 36158875, 2022). "SAA1 has also been linked to the development of IR in adipose tissue in obesity and type 2 diabetes." (PMID 34980155, 2022). "Recently, additional studies have proved that the upregulation of SAA1 is closely related to the occurrence and development of metabolic syndrome, obesity, and diabetes, all risk factors for atherosclerosis." (PMID 36158875, 2022). "GPX3, GHR and SAA1 were removed from further study because they have been reported previously to be associated with obesity." (PMID 33318306, 2020). "A previous report has demonstrated that there exists a correlation between SAA1 genetic polymorphism and obesity among Chinese children." (PMID 31060494, 2019). "In the present study, we aimed to investigate the relation between SAA1 genetic polymorphism and obesity in Chinese children." (PMID 24171731, 2013). "The purpose of this study was to assess SAA1 allelic variants with obesity in young school-age children." (PMID 24171731, 2013). "Because of these species differences over expression of human SAA1 is likely to be the most suitable model when addressing questions related to adipose tissue expression of SAA in human obesity." (PMID 21611116, 2011). "SAA1 genetic polymorphism was associated with obesity in Chinese children." (PMID 24171731, 2013). "In a hierarchical clustering analysis of HFpEF patients, three distinct phenotypic subgroups were identified, with SAA1 levels significantly elevated in both the inflammatory cluster and the obesity/high-CRP cluster." (PMID 41313351, 2026). "Our study was conducted with a primary objective of exploring the direct effects of SAA1 silencing on insulin resistance, which is known to be induced by obesity." (PMID 31060494, 2019). "After the mice had been challenged with a high-fat diet, circulating levels of human SAA1 were similar to the levels seen in human obesity (3.07 ± 0.91 μM; mean ± SD, n = 8)." (PMID 23626589, 2013). "Therefore, the genetic polymorphisms in SAA1 may be associated with obesity." (PMID 24171731, 2013). "The aim of this study was to investigate the effects of adipose tissue-derived SAA1 on the development of insulin resistance and obesity-related inflammation." (PMID 23967285, 2013). "In the process of integrating multi-omics correlation analysis, we identified a set of biomarkers with well-interconnected networks implicated in obesity, such as BPIFA1, BPI, SAA1, PDE1C, Deoxycholic acid, Phthalic anhydride, DL-Alanine, p_Firmicutes, g_Intestinimonas, and g_Turicibacter." (PMID 39609876, 2024). "As the matter of fact, we found that SAA1 concentration in the serum and follicular fluid was slightly elevated in both non-PCOS and PCOS with BMI > 24 kg/m2, which may be associated with obesity." (PMID 34980155, 2022). "However, our study also raises some scientific questions: first, what are the mechanisms that lead to increased SAA1 expression in atherosclerotic diseases (metabolic syndrome, obesity and diabetes), inflammatory, or other factors?" (PMID 36158875, 2022). "Saa1 was identified as an obesity-related gene based on the microarray data of GSE39549." (PMID 31060494, 2019). "Injection of Saa1 inhibitor via caudal vein could effectively inhibit Saa1 and insulin resistance induced by obesity, suggesting that Saa1 inhibitor may be a potentially effective therapeutic strategy for obesity-induced insulin resistance." (PMID 31060494, 2019). "Based on these findings, we drew the hypothesis that Saa1 could mediate the NF-κB pathway in HFD-induced obesity." (PMID 31060494, 2019). "The DEGs Cyp17a1, Cfd and Saa1 were the ones that interacted with obesity-related genes in the interaction network, on the basis of which we speculated that these genes may be related to obesity." (PMID 31060494, 2019).
Obesity (continued). "Moreover, SAA1 was one of the 9 rewired nodes in health- and obesity-NAFL-NASH sequences." (PMID 34419146, 2021). "Hence, we performed microarray/based gene expression analysis, and according to the results obtained, SAA1 was identified as an obesity-related gene on the basis of the microarray data obtained from GSE39549, which was consistent with our initial hypothesis." (PMID 31060494, 2019). "Higher SAA1 levels under long-term HFD treatment could lead to extensive SAA1-derived amyloid deposits, which may consequently lead to the complications associated with HFD-induced obesity and metabolic disorders." (PMID 31060494, 2019). "Furthermore, a previous study indicated that inhibition of the NF-κB pathway could relieve HFD-induced obesity and poor glucose intolerance, and that Saa1 could activate the NF-κB pathway." (PMID 31060494, 2019). "Hence, we conducted the current study with aims of investigating our proposed hypothesis that silencing SAA1 could inhibit the progression of obesity-induced insulin resistance through the NF-κB pathway." (PMID 31060494, 2019). "Therefore, we came to the conclusion that SAA1 could be involved in obesity-induced insulin resistance." (PMID 31060494, 2019). "Thus we speculated that mouse SAA3, which is upregulated in the adipose tissue of obese mice, might be functionally similar to human SAA1 and perhaps represent a link between low-grade inflammation and obesity." (PMID 19513118, 2009). "In obesity, adipose tissue exhibits both increased SAA expression (SAA1 and SAA2 in humans and Saa3 in mice), as well as increased macrophage infiltration." (PMID 37396595, 2023). "SAA1 and SAA2 are highly homologous reactants whose concentration can increase upon infection, trauma, and obesity, whereas SAA3 is a pseudogene and SAA4 is a constitutively expressed minor constituent of the nonacute-phase HDL." (PMID 20847813, 2010). "While the best defined cell source of SAA1 and SAA2 is hepatocytes, SAA1 and SAA2 are also expressed from adipocytes and macrophages under inflammatory conditions in metabolic diseases such as obesity, insulin resistance, and cardiovascular disease." (PMID 32158768, 2020). "This indicates that adipose tissue-derived human SAA1 does not have proinflammatory properties and does not affect obesity-related inflammation or insulin sensitivity in mice." (PMID 23967285, 2013). "Some classical inflammatory biomarkers, including CRP, SAA1, ORM1, and LBP, were determined to further confirm the notably lower inflammatory responses of IBD patients with overweight/obesity than those without overweight/obesity." (PMID 36759757, 2023). "Since humans do not express SAA3, SAA1 and SAA2 may be the major isoforms contributing to inflammation in human obesity." (PMID 35909571, 2022). "The increased circulating SAA levels observed in individuals with obesity are highly correlated with body mass index (BMI), body weight, adiposity, and SAA1 and SAA2 mRNA expression in white adipose tissue (WAT), and are not related to hepatic SAA1 or SAA2 expression." (PMID 37396595, 2023).
breast cancer (20 papers, 2018 to 2025). A primary or metastatic malignant neoplasm involving the breast. "Niu and coworkers reported an accumulation of suppressive granulocytes along with the progression of breast cancer in a TLR2-dependent manner in association with elevated human SAA1 protein production." (PMID 39940756, 2025). "We investigated the role of acute phase SAA1/2 isoforms in tumor growth, host survival, inflammation, and cellular programs using a breast cancer model." (PMID 39336082, 2024). "In the present study, we explore the effects of genetic deletion of SAA1 and SAA2 (hereafter referred to as SAA1-2), the two major SAA proteins in mice, on liver inflammation caused by 4T1 breast cancers." (PMID 36817472, 2023). "This prompted us to further investigate the roles of SAA1-2 in immune cell recruitment to the liver in the 4T1 breast cancer model." (PMID 36817472, 2023). "This study clarifies the negligible contribution of SAA1-2 proteins in liver inflammation in the 4T1 breast cancer model." (PMID 36817472, 2023). "Among them, down-regulation of SAA1 and CCR5 was associated with poor overall survival in breast cancer patients." (PMID 35045088, 2022). "In our study, we showed that the chemokine/CXCR2 axis is another key upstream activator to trigger SAA1 expression in breast cancer." (PMID 31390756, 2019). "Additionally, LEC-released chemokines increased lymphatic invasion by upregulating VE-cadherin phosphorylation and junction disruption, which in turn increased serum amyloid A1 (SAA1) expression in breast cancer cells." (PMID 37056346, 2023). "Furthermore, our findings indicate that the overexpression of SAA1 promotes breast cancer progression by downregulating autophagy in vitro, while the double knockout of Saa1 and Saa2 in vivo induces autophagy as a protective mechanism against cell death." (PMID 36248994, 2022). "We thus propose that the SAA1 gene may potentially be a prognostic candidate for breast cancer metastasis to the lungs." (PMID 35045088, 2022). "Interestingly, the overexpression of SAA1 resulted in decreased Akt activation in the estrogen and progesterone receptor positive breast cancer cell line (MCF7)." (PMID 36248994, 2022). "However, research revealed the unspecific expression of SAA1 in both tumors and TAMs, which can lead to a poor prognosis in breast cancer cases." (PMID 29603594, 2018). "Similarly, the conditioned medium of CAAs has been shown to improve migration/invasion and chemoresistance, as well as to promote EMT in pancreatic cancer cells by the upregulation of serum amyloid A1 (SAA1), which has been associated with poor prognosis in breast cancer." (PMID 36670988, 2023). "Moreover, the overexpression of SAA1 and the resulting inhibition of autophagy promoted proliferation in the two breast cancer cell lines, evident in our results for the DNA replication licensing factor, MCM2, and cell viability as an indication of proliferation." (PMID 36248994, 2022). "Here, we show the novel role of SAA1/2 in modulating the NLRP3 inflammasome, apoptosis, and necrosis in breast cancer." (PMID 39336082, 2024). "For instance, breast cancer derived S100A4 cells resulted in the upregulation of Serum Amyloid A (SAA) proteins, like SAA1 and SAA2, which improved tumor cell adhesion to fibronectin and the recruitment of BMDCs to PMNs." (PMID 35600385, 2022). "We confirmed that the expression of KIF4A, UBE2C and COL11A1 was distinctly increased in BC specimens compared with normal breast specimens, while the expression of SFRP1, SAA1 and RBP4 was distinctly decreased in breast cancer specimens." (PMID 35646102, 2022).